TNF (tumor necrosis factor)
Diseases named in the same sentence as TNF in open-access papers (continued):
Sharing a sentence is not in itself a finding about the gene and the disease.
cancer (continued). "Accordingly, even more complicated roles for TNF-α in cancer cases have emerged." (PMID 31766230, 2019). "Interleukin-10 (IL-10) is immunosuppressive in nature preventing the production of TH1 cytokines (such as IL-2, IFN-γ, and TNF-α), increased circulating levels have been found in several types of cancer including oral squamous cell carcinoma and are correlated to a negative prognosis." (PMID 31750257, 2019). "Co-stimulatory molecules of the tumor necrosis factor (TNF) superfamily are promising cancer immunotherapy molecules, as they have a key role in the generation and expansion of primary immune responses as well as in the establishment of long-term immunological memory." (PMID 30650588, 2019). "The increased levels of TNF-α and other cytokines in the periphery are significant predictors of the development of the active disease and fatigue severity that affect the majority of patients with cancer or those receiving cancer treatments." (PMID 31323874, 2019). "We speculate that miR-21 in TNF-α mRNA positive cancer cells may suppress an autocrine effect of TNF-α to mediate cell death, e.g., via PDCD4." (PMID 30999696, 2019). "Core module analysis indicated that hub genes may play roles in pathways related to cancer, such as the phospholipase D signaling, cAMP signaling, IL-17 signaling, Toll-like receptor signaling, TNF signaling, and MAPK signaling." (PMID 31803246, 2019). "In each of the four cases, multiple events of TNF-α mRNA expression and miR-21 expression in cancer cells could be evaluated." (PMID 30999696, 2019). "We hypothesize that downregulated IGFBP5 expression might release the binding domain of TNFR1 to restore apoptosis induced by TNF-α in cancer cells." (PMID 31886201, 2019). "The major anti-cancer mechanism of NM was the down-regulation of TNF-α-induced NF-κB activation." (PMID 31552177, 2019). "TNF-α inhibited apoptosis in cancer cells by activating the NF-κB signaling pathway." (PMID 31440472, 2019). "As TNFR2 exists without DD, it can enhance proliferation and activation of Tregs via 3 main pathways, namely, NF-kB, activator protein 1 (AP1), and MAPK pathways, therefore avoiding the immunosuppressive effect of TNF which is similar to cancer cells survival pathways." (PMID 31239840, 2019). "Additionally, a study by the National Cancer Institute, USA, using our vector in pet dogs with natural cancers demonstrated that RGD4C/AAVP delivered the cytokine, tumor necrosis factor‐alpha (TNFα), selectively, to spontaneous cancers." (PMID 30808679, 2019). "During immune responses, TNF-α is initially produced to fight cancer cells." (PMID 31485295, 2019). "Indeed, by using the gene set enrichment analysis (GSEA) of hallmarks of cancer, the differentially expressed genes were enriched in categories involved in: TNFα signaling via NF-κB, inflammatory response, IL6 JAK/STAT3 signaling and apoptosis categories." (PMID 31533831, 2019). "The anticancer property of TNF-α is mainly achieved by inducing cancer cell death." (PMID 31766230, 2019). "Several inflammatory mediators, such as TNF-α, IL-6, and IL-10, might have an effect in the initiation and progression of cancer, so the inflammatory microenvironment can be relate to the tumorigenesis of liver." (PMID 31340754, 2019). "In this regard, the blockage of TNF-α might have potential in the management and prevention of chronic disease such as cancer." (PMID 31295906, 2019). "Macrophages play central roles in cancer-inflammation that could be exploited utilizing pharmaceutical control of this novel HIF/COX/TNF mechanism." (PMID 31611882, 2019). "While RHBDL2 appeared as the main effector of TNFα-induced E-cadherin cleavage, our data showed that a basal level of E-cadherin shedding was visible and maintained in cancer cells also upon RHBDL2 depletion, being presumably accountable by the activity of diverse MMPs." (PMID 31783481, 2019).
cancer (continued). "In addition to IL6, interleukin-8 (IL8) and tumor necrosis factor-α (TNF-α) also played some important roles during the evolvement of cancers." (PMID 31781194, 2019). "Responses of single cells exposed to TNF showed transient and variable translocation of NF-κB into the nucleus when measured from time-lapse images, comparable with other human cancer cell lines that express FP-RelA fusions." (PMID 30808860, 2019). "TGFβ has also been shown to induce CSC marker expression in different types of cancers, and TNFα and IL-6 can synergistically activate the TGFβ signaling pathway through activation of NF-κB, the activation of which also induces the expression of EMT-TF and IL-6 secretion." (PMID 31554173, 2019). "TNF-α promoted cancer cell metastasis by upregulating invasive proteins." (PMID 31540489, 2019). "In all four cases, TNF-α mRNA was seen in a small subset of cancer cells at the invasive front." (PMID 30999696, 2019). "Our further research indicated that the altered apoptosis and growth of cancer cells might be caused by the related genes that are downstream and regulated by FOXL2, especially tumor necrosis factor (TNF)." (PMID 31221094, 2019). "Numerous studies have indicated that tumor necrosis factor-alpha (TNF-α) could induce cancer cell survival and metastasis via activation of transcriptional activity of NF-κB and AP-1." (PMID 31766230, 2019). "Additionally, studies have shown that TNF-α increases the metastatic ability of cancer cells through activation of its downstream signaling pathways." (PMID 30791624, 2019). "Previous studies demonstrated that the microglia in the spinal cord was activated in various models of pain (e.g., cancer pain model and nerve ligation), and the upregulation of spinal mRNA levels of inflammation factors (such as TNF-α) was detected temporally after peripheral nerve injury." (PMID 31001066, 2019). "Exhausted CD8+ T cells are characterized by high levels of inhibitory receptors (PD-1/CTLA-4/TIM-3/LAG-3//BTLA/TIGIT) and production of fewer effector cytokines (IL-2/IFNγ/TNF/GzmB) that lead a diminished ability to eliminate cancer cells and their final deletion in the TME." (PMID 32039025, 2019). "A case-in-point is TNF-α, which plays a dual role in the cancer context." (PMID 31137684, 2019). "These hub genes were mainly enriched in the TNF signaling pathway and pathways in cancer." (PMID 31379949, 2019). "We hypothesize that miR-21 may protect both fibroblasts and cancer cells from cell death directed by TNF-α paracrine and autocrine activity." (PMID 30999696, 2019). "iNOS and TNF-α are important molecules that have an impact on carcinogenesis and cancer progression and may influence the clinical response of patients to various treatment modalities." (PMID 30984181, 2019). "Accordingly, the efficient agents that can suppress TNF-α-induced cancer cell progression could be an important part of an attractive and alternative form of cancer therapy." (PMID 31540489, 2019). "Immunotherapy has proven to be an effective option in the treatment of several cancers with high expression of PD-L1; thus, incorporating anti-TNF biologics into this therapeutic regimen may result in improved outcomes for certain types of cancers." (PMID 30755793, 2019). "Specifically, AK2 mediates mitochondrial apoptosis through the formation of an AK2–FADD–caspase 10 complex, whereas NOX4-mediated ROS production induces apoptosis in cancer and normal cells upon stimulation, for instance by incubation with TNF-α, glucose, or anti-cancer drugs." (PMID 31399108, 2019). "Cancer cells can activate the hemostatic system through the expression of pro-coagulant factors including tissue factor and cancer pro-coagulant, release of inflammatory cytokines (i.e., TNF-α, IL-1β) and microparticles, and adhesion to host vascular cells." (PMID 31157239, 2019).
cancer (continued). "Furthermore, TNF-α appears to be favorable for maintenance of cancer cell malignancy and seems to contribute to normal cells’ aberrant proliferation." (PMID 31137684, 2019). "There are, however, reports of an ambiguous role of TNF‐α in cancer progression." (PMID 30548868, 2019). "In cases of inflammation-driven cancers, the release of TNFα and IFN-γ may further enhance the expression of immunoproteasomes to levels that would give grounds for PI targeting." (PMID 29184971, 2018). "AbE was shown to induce apoptosis in cancer cells through the Bax- and the caspase-dependent pathway and to modulate immunological reactions through an increase in the production of tumor necrosis factor-α (TNF-α) and interleukin-8 (IL-8) by macrophages." (PMID 30514293, 2018). "In line, TNFα and IL-6 levels are elevated in the serum of cancer patients." (PMID 30591653, 2018). "Aloe-emodin reduces cancer cell viability through extrinsic (TNF-a and FASL) and intrinsic (cytochrome c/caspase 9) apoptosis pathways, which coincide with deleterious effects on mitochondrial membrane permea-bility and/or oxidative stress via exacerbated ROS production." (PMID 30895270, 2018). "TNF-α is involved in cancer cell proliferation and leukemogenesis." (PMID 29649138, 2018). "This is also the first paper investigating the role of TNF-α −1031T/C in cancer cachexia." (PMID 29802455, 2018). "As cancer cells secretes several inflammatory cytokines such as TNF-alpha and TNF-alpha is one of the important factor associated with M-sec gene expression, inhibiting expression of TNF-alpha can block the formation of TNTs and hence intercellular communication between cancer cells." (PMID 30409198, 2018). "It has been reported that TNF-α can enhance the migration and invasion abilities of cancer cells." (PMID 29467927, 2018). "Furthermore, TNF-α also induces autophagy through antigen stimulation and starvation to block necroptosis in several cell lines, such as L929 cells, lymphocytes, and cancer cells." (PMID 29636841, 2018). "Additionally, IL-12, IL-27, IL-17 and TNF-α regulated PD-L1 expression in inflammatory cells and cancer cells by altering NF-κB, STAT1 and ERK1/2 signaling." (PMID 29690901, 2018). "In addition, both inflammatory chemokine CCL2 and inflammatory factor TNFα have been identified as crucial promoters of cancer progression and metastasis." (PMID 29650964, 2018). "In addition, experimental evidence demonstrated that combined proinflammatory cytokines such as IL-6 and TNF-α are critical for both inflammation and cancer by activating STAT3 and the NF-κB complex." (PMID 30116149, 2018). "With regards to cancer, TNF-α level could swing either way to stimulate the growth, proliferation, invasion and metastasis of cancers, or inversely be beneficial through the induction of cell death." (PMID 30042874, 2018). "In addition, HMGB1 mediates the transcription regulation of E-selectin, TNF-α, BRCA1, and insulin receptor in association with cancer genes." (PMID 29636841, 2018). "We also found that malaria parasite infection could induce IFN-γ and TNF-α secretion, which may lead to improvements in the treatment of some cancers by inducing a massive influx of inflammatory cells as well as the production of Th1 cytokines." (PMID 29764519, 2018). "TNF-α is a master switch from chronic inflammation to cancer." (PMID 29416784, 2018). "PS also targets diverse molecules involved in inflammatory responses, including inducible nitric oxide synthase (iNOS), cyclooxygenases (COX), leukotrienes, NF-κB, TNFα, and interleukins (ILs) for positive health effects against cancer, cardiovascular, and neurodegenerative diseases or diabetes." (PMID 29346311, 2018). "Similarly, research in obese non-cancer patients report reductions in serum cytokine levels and lipid profiles including IL-6, TNF-α, and cholesterol." (PMID 30450163, 2018).
cancer (continued). "Furthermore, combination with ionomycin was proven to be able to enhance the anti-cancer activity of TNFα in the mouse model." (PMID 29506556, 2018). "Tumor necrosis factor-related apoptosis-inducing ligand (TRAIL/Apo2L) belongs to the tumor necrosis factor (TNF) ligand superfamily and has been studied extensively for its potential use as a cancer chemotherapeutic agent due to its low toxicity towards normal tissue." (PMID 29615720, 2018). "Considering that HL is a type of cancer involving cells of the immune system (lymphocytes), as a first step we generated a comprehensive circadian clock/immune system network of genes that pointed to TNF as a major networking partner." (PMID 30065253, 2018). "In the case of cancer development, TNF‐α is a double‐edged sword." (PMID 29632814, 2018). "Many cytokines, like the TNF alpha, often play a pleiotropic role in the setting of malignancy, on one hand promoting inflammation and driving immune side effects and, on the other hand, playing a crucial role in immune surveillance aimed at keeping the malignancy in check." (PMID 30577825, 2018). "Also, because of the beneficial effect of anti-TNF administration in preclinical mouse models, some patients with advanced cancers received TNF blockers." (PMID 29593717, 2018). "As suggested by its name, TNF was described initially as a killer of cancer cells." (PMID 29593717, 2018). "Furthermore, cultured macrophages stimulated with IL‐12 directly kill MC38 cancer cells via production of TNF‐α." (PMID 29963704, 2018). "Leukemic patients present significantly higher proinflammatory cytokines, such as tumor necrosis factor alpha (TNF-alpha) and interleukin 6 (IL-6), at the onset of disease and before cancer therapies, confirming the presence of an inflammatory status in these patients." (PMID 29983896, 2018). "Several cytokines, such as tumor necrosis factor (TNF)-α, interleukins (IL-6, IL-17, IL-12, IL-23, IL-10), transforming growth factor (TGF)-β, and macrophage migration inhibitory factor (MIF) have been linked with both experimental and human cancers." (PMID 29373553, 2018). "p38 also mediates cell death induced by TNFα in cancer cells." (PMID 29752472, 2018). "Instead of targeted TNF neutralization, there are also several indications that might benefit from targeted TNF supply, for example to exploit its anti-cancer properties." (PMID 29751683, 2018). "Another study reported that cytokine levels and the CRP level are clinically relevant for CRC progression, and that measurement of TNF-α serum levels may help identify early cancer progression among patients with CRC." (PMID 29949857, 2018). "Taking into consideration that TNF-α is a major cytokine known to induce cancer cell death through sustained JNK-activation, it can be concluded that the antiproliferative activity of penitrems is associated, in part, with the upregulation of TNF-α and subsequent activation of apoptotic cell death." (PMID 29751615, 2018). "TNFα upregulated IL12RB2 expression in different cancer cell lines." (PMID 30218063, 2018). "Interestingly, the proapoptotic BH3-only protein BIM (encoded by BCL2L11), which is a master regulator of cell death in cancer cells, is a relevant target of miR-19b in spontaneous and TNFα/ActD-induced apoptosis." (PMID 29455644, 2018). "They suggested that nongenomic action of an N-terminally truncated RXRα (tRXRα) could play a role in the crosstalk with TNFα signaling in cancer cells." (PMID 30103423, 2018). "Furthermore, cancer-related systemic inflammation promotes and maintains AF by inducing atrial structural remodeling, such as that in tumor necrosis factor (TNF)-α, nuclear factor (NF)-κB, and macrophage migration inhibitory factor (MIF)." (PMID 30386232, 2018). "As Tregs co-expressing TNFR2 are abnormally abundant in human and murine tumors and can support their growth, blocking TNF-α/TNFR2 pathway could be a therapeutic option in cancer." (PMID 29541073, 2018).
cancer (continued). "Kupffer cells may directly kill cancer cells through secretion of TNF-α and ROS and phagocytose living cancer cells in a Dectin-2-dependent manner to prevent liver metastasis." (PMID 29445150, 2018). "In several cancers, the conserved TNF‐α/NF‐κB axis signaling pathway has been well characterized." (PMID 29377600, 2018). "Our results offer additional confirmation to our speculation that MDM2 can shift the balance of the intracellular events in cancer cells towards pro-angiogenic mechanisms through up-regulation of TNF-α, MMP9, and CXCL10." (PMID 29748481, 2018). "In addition, TNFα can directly kill tumors expressing TNFRs and works in concert with IFNγ to inhibit cancer cell proliferation." (PMID 30400618, 2018). "What do we know about the role of TNF in cancer in patients?" (PMID 29593717, 2018). "Importantly, A20, also known as TNFα-induced protein 3 (TNFAIP3), a key regulator of inflammation and terminator of NF-κB signaling, reduces hepatic inflammation and cancer onset by protecting hepatocytes from TNFα-induced apoptosis under obese conditions." (PMID 30591653, 2018). "Previously, we reported that doxorubicin (Dox), a prototypical reactive oxygen species (ROS)-producing anti-cancer drug, results in oxidation of plasma proteins, including apolipoprotein A-I (ApoA-I) leading to tumor necrosis factor-alpha (TNF-α)-mediated oxidative stress in plasma and brain." (PMID 30100992, 2018). "When the cells were treated with a combination of cetuximab and MEK or JNK, the expression levels of CCL5, CXCL9 and CXCL10 increased, confirming that not one but multiple pathways downstream of the EGFR act in concert to block IFNγ/TNFα -induced chemokine expression by these cancer cell lines." (PMID 30192802, 2018). "Even within the antioxidant polyphenols, however, some compounds and structural groups display more pro-oxidative effects than antioxidant effects and may also potentiate the cytotoxicity of other drugs (e.g., TNF-α) in cancer cells." (PMID 29587429, 2018). "Many preclinical data suggest that TNFα may be used as a highly specific anti-cancer drug against many types of tumors." (PMID 29506556, 2018). "Fractalkine protects myotubes from TNFα induced damage in muscle and may protect against cancer cachexia." (PMID 30513792, 2018). "We previously hypothesized that TNF-α elevated in the periphery and in brain following cancer chemotherapy plays a central role in CICI." (PMID 30100992, 2018). "The pro-inflammatory cytokine mediators include tumor necrosis factor-alpha (TNF-α), interferon alpha (IFN-α), interleukin-2 and -8 (IL-2 and IL-8), causing inflammation and contribute to cancer development, primarily by causing oxidative stress and DNA damage." (PMID 30607173, 2018). "However, HA-ARD1 and its nonphosphorylatable mutant HA-ARD1 S209A restrained the phosphorylation levels of S6K1, while the phosphorylation-mimic mutant HA-ARD1 S209E increased S6K1 phosphorylation in TNFα-treated cancer cells." (PMID 30154412, 2018). "However, TNF-α-induced activation of the transcription factor nuclear factor- (NF-) κB and NF-κB-driven expression of prosurvival factors is a major obstacle to preventing the cancer therapeutic efficacy of TNF-α." (PMID 29849917, 2018). "As a multifunctional cytokine, TNF-α has a complex role in the treatment of cancer." (PMID 29467927, 2018).